IRS1 (insulin receptor substrate 1)
Diseases named in the same sentence as IRS1 in open-access papers (continued):
Sharing a sentence is not in itself a finding about the gene and the disease.
prostate carcinoma (26 papers, 2006 to 2025). A carcinoma that arises from epithelial cells of the prostate gland. "The IRS1/2 ratio has been shown to be significantly lower in malignant prostate tumors than in benign prostatic tissue and functional polymorphisms in IRS1 have been associated with a more advanced Gleason score." (PMID 25883651, 2015). "IRS1/2 have also been implicated in the progression and etiology of prostate cancer." (PMID 25883651, 2015). "On the other hand, the abnormal activation of IRS1 promotes prostate cancer progression through the IRS1/SREBP-1 axis." (PMID 39771106, 2024). "The previous literature has reported that the inhibition of IRS1 can suppress prostate cancer proliferation." (PMID 39771106, 2024). "miR-21-5p inhibition downregulates SREBP1 expression by suppressing insulin receptor substrate 1 (IRS1)-mediated transcription and inducing senescence in prostate cancer cells, which is reversed by miR-21-5p overexpression." (PMID 36835100, 2023). "For instance, IRS1 overexpression contributes to cancer progression with the worst clinical outcomes for breast, pancreatic, and prostate cancers through PI3K/Akt and MAPK/ERK signaling pathways." (PMID 36768755, 2023). "We found that P-ERK was significantly reduced after knocking down IRS-1 in DU145 and PC-3 cells, while there was little change in P-AKT, suggesting that IRS-1 mainly activates the ERK signaling pathway in prostate cancer." (PMID 33109107, 2020). "We have previously demonstrated that over-expression of miR-203 significantly down-regulates IRS-1 protein expression, while previous studies have shown that over-expression of miR-203 can inhibit proliferation of prostate cancer cells." (PMID 33109107, 2020). "We then examined the effect of IRS-1 knockdown on prostate cancer cell proliferation by MTT, colony formation and EdU incorporation assay compared with overexpression of miR-203." (PMID 33109107, 2020). "To further investigate the molecular mechanism of miR-203 and IRS-1 in prostate cancer, we primarily detected the phosphorylated AKT (P-AKT) and phosphorylated ERK (P-ERK) protein levels to detect the activation on these two signaling pathways." (PMID 33109107, 2020). "miR-203 can inhibit ERK signaling pathway and inhibit the proliferation of prostate cancer cells by targeting IRS-1." (PMID 33109107, 2020). "Further research confirmed that miR-203 mediated down-regulation of IRS-1 inhibited prostate cancer cell proliferation, induced cell cycle G0/G1 arrest, and decreased ERK activation." (PMID 33109107, 2020). "In prostate carcinoma cells, IRS-1:IRS-2 ratios are lower in malignant vs. benign prostate tissue and decreased IRS-1 expression is associated with increased motility and invasion, functions associated with later disease stages." (PMID 31393907, 2019). "Despite the consistency of these data, reports from other labs have suggested a role for IRS-1 in increasing cell adhesion and decreasing cell motility in prostate cancer cells." (PMID 17043687, 2006). "The results showed that the expression level of IRS-1 in invasive prostate cancer stroma was significantly higher than that of normal prostate stroma (* P < 0.05), suggesting that IRS-1 may be involved in the metastasis of prostate cancer." (PMID 33109107, 2020). "In addition, we explored the relationship between IRS-1 and prostate cancer metastasis, and found that down-regulation of IRS-1 can inhibit tumor migration." (PMID 33109107, 2020). "Moreover, we found that both miR-203 overexpression and IRS-1 down-regulation significantly inhibited prostate cancer metastasis." (PMID 33109107, 2020). "In prostate cancer, miR-203 can regulate multiple target genes, IRS1 being one of them." (PMID 33109107, 2020). "Indeed, IRS-1 down-regulation can inhibit the migration of prostate cancer cells by down-regulating the Slug protein." (PMID 33109107, 2020).
prostate carcinoma (continued). "In addition, IRS2 promotes cell motility and invasion in neuroblastoma and mesothelioma cells, while overexpres­sion of IRS1 in prostate carcinoma cells decreases tumor cell motility." (PMID 23112878, 2012). "In contrast to IRS-2, IRS-1 may suppress cell migration because expression of IRS-1 in LnCAP prostate carcinoma cells decreases their motility." (PMID 19534786, 2009). "Therefore, we speculate that down-regulation of IRS-1 may inhibit the proliferation of prostate cancer." (PMID 33109107, 2020). "In addition, USP9X interacted with endogenous IRS-1/2 in PC3 human prostate cancer cells." (PMID 30338032, 2018). "In the treatment of prostate cancer resistance, inhibition of AKT/mTOR will feedback enhance MAPK signaling, and conversely, MEK inhibitors will relieve S6K’s inhibition of IRS1, activate the PI3K-AKT pathway, and lead to compensatory escape." (PMID 41368570, 2025). "Cur has also been shown to improve the sensitivity of prostate cancer cells to PTX through targeting mitogen and stress-activated kinase 1 (MSK1) and insulin receptor substrate-1 (IRS-1) signaling." (PMID 37623653, 2023). "Compared to the control group, either knockdown of IRS-1 or overexpression of miR-203 significantly decreased cell migration, indicating that down-regulation of IRS-1 can inhibit the migration of prostate cancer cells." (PMID 33109107, 2020). "Overexpression of miR-143 abolished IGF-I-induced chemoresistance to docetaxel treatment, decreased expression levels of IGF-I, IRS1, and vascular endothelial growth factor (VEGF) in prostate cancer cell lines." (PMID 29291019, 2017). "Identical results were obtained when His-IRS1 and His-IRS1 S1101A mutant plasmids were transfected into PC3-LN4 prostate cancer cells." (PMID 26956053, 2016). "In prostate cancer cells, co-inhibition of epidermal growth factor receptor and IGF-1R reduced phosphorylation of IRS-1 and its interaction with RAD51, suppressing HR and increasing radio-sensitivity." (PMID 26510816, 2015). "IRS-1 mediates IGF-1-dependent growth in these cells, which has also been observed for hepatocellular and prostate carcinoma, medulloblastoma and malignant pleural mesothelioma cell lines." (PMID 19534786, 2009). "Expression of both IRS-1 and IRS-2 is reported to be increased in hepatocellular, pancreatic and prostate cancer and malignant pleural mesothelioma." (PMID 19534786, 2009). "miRNA-21 overexpression increases cell proliferation and migration, as well as the levels of insulin receptor substrate 1 (IRS1), sterol regulatory element-binding protein 1 (SREBP-1), fatty acid synthase (FASN) and acetyl-CoA carboxylase (ACC) in human prostate cancer cells." (PMID 35457012, 2022). "To prove whether IRS-1 is involved in the regulation of prostate cancer metastasis, we first examined the migration ability of DU145 and PC-3 after knocking down IRS-1 or overexpressing miR-203." (PMID 33109107, 2020). "Therefore, miR-203 probably inhibits prostate cancer metastasis in vivo by IRS-1-mediated the down-regulation of Slug rather than the EMT classical proteins like E-cadherin and Vimentin." (PMID 33109107, 2020). "To further prove whether miR-203 regulates cell proliferation and metastasis in Prostate Cancer by targeting IRS-1, we examined the proliferation of PC-3/DU145-miR-203 cells with or without IRS-1 rescue through CCK8 and colony formation assay." (PMID 33109107, 2020).
Cognitive impairment (22 papers, 2017 to 2025). Abnormal cognition is characterized by deficits in thinking, reasoning, or remembering. "Increased phosphorylation of this IRS‐1 residue as a result of increased mTORC1 activity has been directly associated with brain IR and cognitive impairment." (PMID 38010200, 2023). "PF pairs prevent tau hyperphosphorylation and protect cognitive impairment by restoring SOCS2/IRS-1 signal pathway." (PMID 35449815, 2022). "In summary, our study supports the notion that the chronic consumption of HFD induces cognitive impairments through the adipoR1/AMPK/IRS1 axis, leading to the development of AD-like pathology." (PMID 31963819, 2020). "Few studies have reported the relationship between streptozotocin (STZ)-induced type 1 diabetes-related cognitive impairment and phosphorylation of neural IRS1 at Ser sites." (PMID 31426549, 2019). "Several biomarkers were also highlighted as potential biomarkers of GDM-related cognitive impairment such as AGEs, serine-phosphorylated IRS-1 and inflammatory markers such as tumor necrosis factor α (TNF-α), high-sensitivity C-reactive protein (hs-CRP), leptin, interleukin 1β (IL-1β), and IL-6." (PMID 30563117, 2018). "And aberrant IR/IRS-1 signaling might be related to mood and cognitive impairment." (PMID 34149862, 2021). "PF can improve cognitive impairment and the defect of insulin signal transduction by upregulating the expression of p-PI3K and p-Akt protein and downregulating the expression of p-IRS-1 protein." (PMID 35449815, 2022). "HIV-infected women with cognitive impairment have higher levels of sIR in plasma and CSF when compared to HIV-negative women, as well as higher insulin binding to sIR and lower levels of IRS-1 tyrosine phosphorylation in plasma." (PMID 35720083, 2022). "EGCG (2 g/day) upregulates IRS1/Akt and ERK/CREB/BDNF (brain-derived neurotrophic factor) signalling pathways, significantly decreasing IR and cognitive impairment in HFD and high-fructose-induced mouse models of cognitive impairment." (PMID 37036026, 2023). "This suggests that the cognitive impairment of AD mice may be related to the insulin signaling pathway, and DSS intervention may reduce the accumulation of neuropathological products by regulating the IRS1/GSK3β/Wnt‐β‐catenin pathway, thus playing a cognitive protective role." (PMID 39344343, 2024).
colorectal cancer (22 papers, 2012 to 2024). A primary or metastatic malignant neoplasm that affects the colon or rectum. "Interestingly, data from epidemiological studies suggest that specific genetic polymorphisms in the IRS-1 and 2 genes are associated with decreased or increased risk of developing colorectal cancer." (PMID 36900240, 2023). "Another peptide that disrupts the interaction between IRS1 and p110α E545K in colorectal cancer destabilized the p110α protein, reduced AKT phosphorylation, and slowed the growth of tumors expressing p110a E545K." (PMID 37891174, 2023). "Numerous studies in other cancer types have shown the oncogenic capacity of IRS-1 and 2, but little is known of their prognostic impact in colorectal cancer." (PMID 36900240, 2023). "Studies demonstrated that Insulin receptor substrate 1 (IRS1) promoted tumor growth in colorectal cancer targeted by miR-30a-5p and was stabilized by RNA-bindingprotein lin-28 homolog B (LIN28B)." (PMID 34488531, 2021). "NT-157, the allosteric inhibitor of IRS1/2, was recently found to limit colorectal cancer metastasis to the liver by reducing the trophic support received by stromal myofibroblasts or HSCs." (PMID 30695023, 2019). "Density of IRS1 immunostaining in paired colonic epithelium, primary colorectal cancer and synchronous liver metastasis." (PMID 22558377, 2012). "Colorectal cancer (CRC) is associated with lifestyle factors that affect insulin/IGF signaling, of which the insulin receptor substrate 1 (IRS1) is a key transducer." (PMID 22558377, 2012). "Independent samples t-test of IRS1 expression according to the individual and pathological features of the primary colorectal cancer cases (n = 163)." (PMID 22558377, 2012). "Similarly, in a colorectal cancer sample, it was shown that miR-497-5p inhibits tumor growth by targeting the IRS1 gene that influences several signaling pathways, including MAPK." (PMID 33374439, 2020). "Further research showed that miR-145 inhibits N-RAS and IRS1 expression to suppress AKT and ERK1/2 activation and VEGF expression in colorectal cancer." (PMID 25124875, 2014). "For example, in a survey of 41 breast and 27 colorectal cancer cell lines, the expression levels of IGF-1R, IRS-1, IRS-2, and IGF-2 were correlated with positive predictive values for h10H5." (PMID 22952934, 2012). "Based on previous findings and published validated targets for miR-7 such as EGFR, PAK1, RAF1, IRS1/2 and CD98, it is fair to hypothesize that this miR may be involved in regulating intracellular signaling, growth and differentiation of colorectal cancers." (PMID 22529906, 2012).
pancreatic cancer (19 papers, 2005 to 2025). "IRS1 has been linked to the development and progression of various cancers, including breast, prostate, and pancreatic cancers." (PMID 36768755, 2023). "Another study showed that concurrent blockade of IGF1R and its EGFR/Her-2 simultaneously inhibited the pancreatic tumor growth and the stimulation of IRS-1, Akt, and MAPK phosphorylation." (PMID 36556296, 2022). "It has been reported that IRS-1 contributes to the excessive growth stimulation in human pancreatic cancer." (PMID 34443299, 2021). "LncRNA CRNDE acts as a ceRNA in pancreatic cancer and sponges miR-384 to promote its progression via upregulating IRS1 expression." (PMID 32231464, 2020). "First, the IL-4-dependent tyrosine phosphorylation of IRS-1 and -2, overexpressed in human pancreatic cancer, was analysed." (PMID 15714203, 2005). "Studies have shown that silencing IRS1 could enhance chemotherapy sensitivity in patients with breast and pancreatic cancer." (PMID 35387129, 2022). "IRS1 also regulates pancreatic cancer cell growth and gemcitabine response." (PMID 30770779, 2019). "Therefore, our studies suggested that PDGFRα and KIT downregulation in pancreatic cancer leads to decreased p70S6K phosphorylation at Ser 418, and increased IRS-1 phosphorylation at Ser 636 via increased PI3K/AKT mTOR/P70S6K signaling." (PMID 27014871, 2016). "We finally elicit the deletion of a looping of IRS1-a key insulin signaling gene-significantly impeding pancreatic cancer cell growth, indicating that looping-mediated insulin signaling might act as an oncogenic pathway to promote pancreatic cancer progression." (PMID 38927910, 2024). "Furthermore, since dysregulation of IRS1/ERK/AKT pathways is frequently linked to cancer predisposition and poor prognosis, our findings may also have important implications for pancreatic cancer etiology and chemotherapy." (PMID 30770779, 2019). "In this study, we confirmed the relationship between TNS2 expression and the expression of Axl, IRS-1, PDK1 and Glut4 in pancreatic cancer patients." (PMID 30419905, 2018). "This receptor and its adaptor proteins IRS-1 and IRS-2 are expressed in pancreatic cancer cell lines as well as in human PDA." (PMID 25885700, 2015). "Furthermore, we validated several miRNAs nodes that have been dysregulated during gemcitabine resistance, and subsequently confirmed the role of miR-30a in pancreatic cancer cell sensitization to chemotherapy, mainly through SNAI1/IRS1/ERK/AKT pathway." (PMID 30770779, 2019). "Moreover, we found a positive relationship between TNS2 expression and the expression of Axl, IRS-1, PDK1 and Glut4 in pancreatic cancer patients." (PMID 30419905, 2018). "Therefore, we further examined the correlation of TNS2 expression and expression of Axl, IRS-1, pyruvate dehydrogenase kinase 1 (PDK1) and glucose transporter type 4 (Glut4) in tissue of 33 patients with pancreatic cancer." (PMID 30419905, 2018). "Pancreatic cancers not only overexpress multiple growth factors including members of the insulin-like growth factor (IGF) family like IGF-I, but also overexpress the intracellular signal transducers of this pathway, IRS-1 and IRS-2." (PMID 15714203, 2005).
endothelial dysfunction (18 papers, 2010 to 2025). In vascular diseases, endothelial dysfunction is a systemic pathological state of the endothelium (the inner lining of blood vessels) and can be broadly defined as an imbalance between vasodilating and vasoconstricting substances produced by (or acting on) the endothelium. "In this way, insulin-resistant subjects carrying IRS-1 polymorphisms showed that impaired endothelial insulin signaling and reduced NO activity contributed to endothelial dysfunction." (PMID 34440804, 2021). "The mechanism underlying endothelial dysfunction may therefore involve activation of NF-κB, which by inhibiting IRS-1/PI3-kinase signal transduction, attenuates NO production." (PMID 22216328, 2011). "However, whether sunitinib causes endothelial dysfunction and hypertension via IRS-1/PI3K/AKT/eNOS pathway remains to be demonstrated." (PMID 33841146, 2021). "Specifically, hypertension‐induced endothelial dysfunction disrupts the insulin receptor substrate‐1 (IRS‐1)/PI3K/Akt signaling pathway, reducing glucose uptake in skeletal muscle and adipose tissue." (PMID 41143273, 2025). "Angiotensin also activates JNK and MAPK pathways in endothelial cells, which leads to increased serine phosphorylation of IRS-1, impaired PI-3 kinase activity and finally endothelial dysfunction and probably apoptosis." (PMID 20634940, 2010).
steatosis (18 papers, 2012 to 2024). Increased lipid within the cytoplasm of cells. "Previous studies have shown the decrease in IRS1 expression associated with increased fat synthesis and steatosis." (PMID 37780625, 2023). "Compared to CAF, CAFQ lowered plasma glucose, increased liver IRS‐1 mRNA expressions, increased pancreatic β‐cell insulin immunoreactivity, and lowered hepatocyte degeneration and microvesicular steatosis." (PMID 37970433, 2023). "In subjects with steatosis, the expression levels of Irs1 were significantly increased, wheras those of Irs2 were significantly decreased." (PMID 27708333, 2016). "Additionally, HNK alleviated hepatic IR by promoting the phosphorylation of IRS1 in NCTC1469 cells with steatosis." (PMID 33354276, 2020). "Moreover, in hepatitis C, increased CD2-associated proteins have been demonstrated to influence lipid metabolism through the IRS1-Akt-AMPK-HSL pathway, causing deactivation of hormone-sensitive lipase and consequent augmentation of lipid droplet accumulation, ultimately promoting steatosis." (PMID 38550602, 2024). "Compared to CON, CAF increased body weight gain, plasma insulin, plasma glucose, decreased liver IRS‐1, AMPK mRNA expressions, and pancreatic β‐cell insulin immunoreactivity, and developed hepatocyte degeneration and microvesicular steatosis." (PMID 37970433, 2023). "Namely, their study pointed out a significant effect in decreasing the degree of steatosis, decreasing the SOCS3 expression level, and increasing the Irs-1 expression level in Wistar rats treated with Exenatide." (PMID 35454311, 2022). "In vitro, silencing of FGFR4 in primary mouse hepatocytes resulted in cell autonomous upregulation of IRS1, but not in an improvement of insulin signaling, which is likely mediated by a decrease in steatosis." (PMID 36586437, 2023). "In this model, the downregulation of PTEN led to a reduction of insulin receptor substrate 1 (IRS1) expression, and both events seemed involved in the altered lipid metabolism leading to steatosis, since the overexpression of either PTEN or IRS1 prevented the development of large lipid droplets." (PMID 25522003, 2014). "Thus, IRS expression was again assessed in cell culture model of steatosis and increased IRS-2 mRNA levels were found at low insulin concentrations, while our highest insulin condition resulted in increased IRS-1 mRNA." (PMID 22745692, 2012). "ER stress induces serine phosphorylation of insulin receptor substrate 1 (IRS-1) via the c-Jun N-terminal kinase (JNK) pathway, which then inhibits insulin responses in cultured liver cells enhancing lipogenesis, affecting hepatic steatosis, and influencing insulin resistance." (PMID 31011483, 2019). "In the present study, we demonstrated that insulin and/or IGF1 signaling mediated through Irs1 is directly contributed to the development of HCC, independent of the development of steatosis." (PMID 28710407, 2017).